ST6GAL1 (ST6 beta-galactoside alpha-2,6-sialyltransferase 1)
Diseases named in the same sentence as ST6GAL1 in open-access papers (continued):
Sharing a sentence is not in itself a finding about the gene and the disease.
inflammation (2 papers, 2019 to 2021). Aberrant reaction of the microcirculation characterized by movement of fluid and leukocytes from the blood into extravascular tissues. "Circulatory ST6Gal-1 deficiency also resulted in more acute Th2 pulmonary inflammation with excessive eosinophil infiltration and elevated inflammatory cytokine release in OVA-sensitized mice." (PMID 30778346, 2019). "We showed here that NTHI-elicited acute lung inflammation is more severe in mice with circulatory ST6Gal-1 insufficiency, as characterized by a 1.5-fold exaggeration in the already severe neutrophil infiltration into the airway." (PMID 30778346, 2019).
hematological malignancies (1 paper, 2022). "A possible contribution of ST6Gal1 to hematological malignancies has been much less well-studied." (PMID 35371997, 2022).
infectious disease (1 paper, 2025). A disorder directly resulting from the presence and activity of a microbial, viral, or parasitic agent in humans. "We find a similar association in a human cohort between ST6GAL1 and Paraprevotella, both of which have been linked with immune and infectious diseases." (PMID 41413022, 2025).
kidney disease (1 paper, 2022). "Besides, the elevated ST6GAL1 level was associated with slower kidney disease progression." (PMID 35016642, 2022).
ST6GAL1 also shares sentences with these, for which no sentence is quoted: colon adenocarcinoma (5 papers); acute lymphoblastic leukemia (2); cervix squamous cell carcinoma (2); gastric adenocarcinoma (2); T-cell acute lymphoblastic leukemia (2); acute leukemia (1); adenoma (1); alcoholism (1); bacterial infections (1); benign prostatic hyperplasia (1); benign tumor (1); bipolar disorder (1); breast adenocarcinoma (1); Burkitt lymphoma (1); cardiac arrest (1); cervical intraepithelial neoplasia (1); chronic pancreatitis (1); colorectal adenoma (1); colorectal polyps (1); common variable immunodeficiency (1); conduct disorder (1); congenital disorder of glycosylation (1); Crohn disease (1); cutaneous melanoma (1); endothelial dysfunction (1); glomerulosclerosis (1); hyper-IgM syndrome (1); Insulin resistance (1); keratoacanthoma (1); latent infection (1).
A further 13 diseases each share a sentence with ST6GAL1 in 1 paper.